CGAS (cyclic GMP-AMP synthase)
Diseases named in the same sentence as CGAS in open-access papers (continued):
Sharing a sentence is not in itself a finding about the gene and the disease.
tumor (continued). "The combination of Mn2+ and tumor‐derived mtDNA activated the cGAS‐STING pathway, reprogramming M2‐like TAMs to an M1 phenotype and inducing T cell‐mediated antitumor immunity." (PMID 40787898, 2025). "Mechanistically, cytosolic DNA from irradiated tumour cells activated the cGAS/STING pathway in dendritic cells, leading to type I interferon production." (PMID 41226343, 2025). "STING knockout increased tumor susceptibility in colitis-related mice cancer models, inevitably indicating that the SASP-promoted cGAS-STING axis prevents tumorigenesis by reinforcing senescence or enhancing the immune-targeted clearance of aberrant cells." (PMID 40552295, 2025). "The cGAS/STING signaling has been shown to exert tumor‐suppressing effects via production of IFN‐I, promotion of cellular senescence through senescence‐associated secretory phenotype (SASP), and activation of antigen‐presenting cells." (PMID 41117130, 2025). "Recently, the cGAS-STING pathway has emerged as a major focus of research in the areas of anti-tumor immunity, autoimmune diseases, and inflammatory diseases." (PMID 40621423, 2025). "Antitumor efficacy was demonstrated in a 4T1 tumor‐bearing mouse model, with cGAS‐STING activation shown to enhance T cell‐mediated immunity." (PMID 40787898, 2025). "Cyclic GMP-AMP synthase (cGAS)-stimulator of interferon genes (STING) pathway is a key mediator of anti-tumor immunity." (PMID 39885557, 2025). "Studies show that the cGAS-STING pathway plays key roles in immune responses as well as tumor development." (PMID 39757995, 2025). "Radiation-induced microparticles containing double-stranded tumor DNA led to activation of the cGAS/STING pathway in macrophages, promoting γδ T cell recruitment through CCL20 signaling." (PMID 41392975, 2025). "These micromotors can induce ferroptosis and immunogenic cell death, deliver tumor antigens, and activate the Mn2+‐dependent cGAS‐STING pathway." (PMID 40405693, 2025). "cGAS, a crucial member, serves as a cytoplasmic DNA sensor involved in tumor immune surveillance 13, influencing both the DNA damage response and the tumor microenvironment 14,15." (PMID 40657359, 2025). "In conclusion, our data suggest that probiotic BF839 induced tumor suppression was regulated by the cGAS-STING pathway." (PMID 40231233, 2025). "In the previous research, we have verified that Mn2+ can activate the cGAS‐STING pathway of tumor cells, thus improving the adaptive immune response." (PMID 39792614, 2025). "NR1D1 enhances anti-tumor immunity via activating cGAS-STING pathway and promoting CD8+ T-cell responses." (PMID 40567603, 2025). "Unexpectedly, γδ T cell‐intrinsic cGAS was dispensable for anti‐tumor function, suggesting that γδ T cells incorporated environmental cGAMP during this process." (PMID 39573933, 2025). "Preclinical studies have supported the potential use of PARPi as an immunostimulatory agent in combination with ICIs through the activation of cGAS‐STING signaling and the increase of tumor mutational burden in TNBC with either gBRCAm or gBRCAwt." (PMID 41360639, 2025). "In HCC, macrophages, such as Kupffer cells (KCs), can be activated by the cGAS-STING pathway when a large amount of DNA is released from dying tumor cells or when exogenous STING agonists are used." (PMID 40098962, 2025). "On the other hand, increasing evidence suggests that the cGAS-STING pathway induces an immunosuppressive tumor microenvironment." (PMID 39975558, 2025). "Noticeably, cGAMP promoted the aggregation of F4/80+ cells at the edge of B16-F10 tumors (Fig. EV6B), while Zyxin deletion inhibited tumor growth at a level comparable to cGAS-STING activation." (PMID 39304793, 2024). "High levels of TREX1 in tumor cells can lead to decreased activation of the cGAS-STING pathway, allowing cancer cells to avoid detection and destruction by the immune system." (PMID 38881902, 2024).
tumor (continued). "In vitro assays demonstrated that RTRT induced DNA damage and dsDNA in tumor cells, activating the cGAS-STING pathway." (PMID 39736508, 2024). "Concurrently, the DNA damage resulting from tumor eradication triggers activation of the cGAS–STING pathway, thereby establishing the combined utilization of PTX as a promising chemoimmunotherapeutic strategy." (PMID 38715912, 2024). "Sorafenib combined with STAT3 knockdown was revealed to accelerate HCC cell apoptosis and encourage cGAS-STING-mediated anti-tumor immunity." (PMID 38807595, 2024). "Exposure to ionizing radiation or chemotherapeutic treatments, such as platinum-based drugs, can also induce DNA double-strand breaks and activate the cGAS-STING pathway to maintain tumor cell survival." (PMID 39464890, 2024). "Tumor-derived DNA can activate the STING pathway at the level of cGAS in host immune cells or, alternatively, tumor-derived cGAMP can be transferred to host APCs thereby directly activating STING." (PMID 39020402, 2024). "RT can induce a variety of immune-related pathways through tumor cells destruction, including the cyclic guanosine monophosphate-adenosine monophosphate synthase (cGAS)–stimulator of interferon genes (STING) pathway." (PMID 37921958, 2024). "A noteworthy manifestation of this immunogenicity is the activation of the cGAS-STING signaling pathway within tumor cells, leading to type I IFNs production." (PMID 38323315, 2024). "As the major regulator in the promotion of metastasis of CIN tumours, the roles of cGAS‐STING are complex and paradoxical." (PMID 39183480, 2024). "Elevated R-loop formation and higher autophagic flux in BRCA2-deficient cells can activate the cGAS-STING pathway, potentially leading to chronic cellular stress and influencing tumor development and immune surveillance." (PMID 39595558, 2024). "Responding to ROS, cisplatin and camptothecin were released at the tumor site, triggering activation of the cGAS-STING pathway through double DNA damage." (PMID 38185685, 2024). "Roles of cGAS-STING signaling in tumor biology are complex, particularly with integrating antitumor immunity from NK cells and CD8+ T lymphocytes, TAM-mediated immune suppression, and effects of STING-induced senescence and microenvironmental regulation." (PMID 39304793, 2024). "Methionine regulates tumor immunity by regulating the activity of cyclic GMP-AMP synthase (cGAS), so the tumor immune response can be improved by controlling dietary methionine intake." (PMID 38361936, 2024). "Chemotherapy‐triggered DNA damage activated the cGAS‐STING pathway and cGAS inhibitors synergize with chemotherapeutics in tumor killing." (PMID 38145335, 2024). "The cGAS-STING pathway plays a pivotal role in regulating tumor cell senescence and apoptosis and bolstering antitumor immunity, making it a critical component in antitumor mechanisms." (PMID 39834588, 2024). "In turn, those therapeutic methods can strengthen the stimulation of the cGAS-STING pathway as they can induce cell death and the release of tumor-associated antigen." (PMID 39125107, 2024). "During tumor progression, the interaction between externally released DNA from tumor cells and the cytosolic DNA sensor cGAS triggers the production of cyclic GMP-AMP (cGAMP)." (PMID 39420203, 2024). "CGAS-STING signaling pathway mediated anti-tumor immune response by inducing cytoplasmic DNA up-regulated type I interferon (IFNs)." (PMID 39054486, 2024). "Many human tumors are resistant to immunotherapy because they downregulate STING signaling by various mechanisms, a fact that testifies to the importance of the cGAS-STING pathway in mediating tumor response to ICB therapy." (PMID 39050705, 2024).
tumor (continued). "Local immune response, up- and downregulation of PD1/PDL1, VEGF, FGF/FGFR, cGAS-STING signaling pathways and specific gene mutations all contribute to tumor response to particular treatments." (PMID 38611044, 2024). "cGAS functions as an essential DNA sensor, which senses the cytoplasmic dsDNA and activates the anti-tumor immune response." (PMID 38177099, 2024). "POLQ inhibition represents a synthetic lethal approach to blocking tumor growth while concurrently activating the cGAS-STING signaling pathway, enhancing tumor immune infiltration and offering a novel therapeutic strategy." (PMID 39595558, 2024). "Together, these data support the preferential crosstalk between tumor cGAS and endothelial STING in live caner, which is highly angiogenic." (PMID 38177099, 2024). "The release of DNA by tumor cells can induce senescence by activating the cGAS-STING signaling pathway, triggering senescence through the NF-κB signaling cascade or SASP factor secretion." (PMID 39834588, 2024). "Three weeks later, tumour formation was significantly reduced in cGAS-knockdown mice (37.5%) versus controls (100%)." (PMID 39080411, 2024). "As an important target in antiviral immunity and tumor immunotherapy, it is also imperative to guide the development of novel targeted drugs against the cGAS-STING signaling pathway." (PMID 38693578, 2024). "Neutralizing TGF-β1 or activating cGAS-STING pathway not only antagonized the effect of Tregs on the tumor antigen presentation and immunosuppressive signal in MM cells, but also mitigated the pro-tumorigenic effect of Tregs in the mouse model." (PMID 38773213, 2024). "In summary, this study provided a nanotechnology‐based Mn–Zn dual‐ion delivery strategy to enhance the cGAS‐STING‐mediated anti‐tumor immunotherapy via." (PMID 38225693, 2024). "The cGAS‐STING pathway is a key regulator of tumor CD8+ T cell infiltration and is regulated by RECQL4." (PMID 38381090, 2024). "In BRCA1-deficient TNBC, olaparib treatment increased tumor infiltration and CD8+ T cell activation in vivo through the cGAS/STING pathway as well." (PMID 38542143, 2024). "We found that the antitumor effects of zebularine promote the processing and presentation of tumor antigen through the cytoplasmic cGAS-STING DNA-sensing pathway, thereby enhancing tumor killing by T cells." (PMID 38755254, 2024). "The synthesis of unsaturated fatty acids in tumor cells leads to lipid peroxidation and mitochondrial damage, resulting in mitochondrial DNA leakage, ultimately activating the cGAS-STING innate immune pathway." (PMID 39170694, 2024). "In this review, we will cover the effects of cGAS-STING signaling in the tumor microenvironment, with a focus on its role in the response of tumors to radiation therapy." (PMID 38659582, 2024). "Compared with cGAS‐/STING‐ Tfh tumor cells, the DNA repair pathway was enriched in cGAS+/STING+ Tfh tumor cells according to the scRNA‐seq analysis of AITL." (PMID 38145335, 2024). "The cGAS-STING pathway-related agonists can synergistically interact with PD-L1 inhibitors to exert anti-tumor immune functions." (PMID 39464890, 2024). "For example, the chromosomal instability in tumor cells can lead to sustained activation of the cGAS-STING pathway, inducing chronic inflammation and immunosuppressive TME, desensitizing cells to inflammatory responses and aiding tumor cells in immune escape." (PMID 38999073, 2024). "Prolonged activation of downstream effector programs associated with cGAS-STING leads to persistent inflammation and facilitates tumor progression." (PMID 38240703, 2024). "In tumor cells, the released DNA in the cytoplasm can be sensed by cGAS, which triggers the activation of the cGAS-STING pathway activation and subsequently induces an immune response." (PMID 38724978, 2024).
tumor (continued). "In summary, these results demonstrate that tumor exosomal ENPP1‐mediated extracellular 2′3′‐cGAMP hydrolysis inhibits cGAS‐STING signaling in bystander cells." (PMID 38498770, 2024). "In mouse models and clinical patients, activation of the cGAS-STING pathway has been proven to reduce tumor growth and improve immunogenicity." (PMID 38195584, 2024). "In conclusion, our results showed an interplay between tumor intrinsic genomic instability and cGAS-STING innate immune signaling as well as the downstream STAT1 signaling." (PMID 38167507, 2024). "Our results also raise the possibility that disrupting hydrolytic activity of tumor exosomal ENPP1 in ENPP1 blocking therapy is a previously unrecognized mechanism in cGAS‐STING pathway." (PMID 38498770, 2024). "Oxidative DNA damage can remodel the tumor immune microenvironment through the cGAS-STING pathway, which improves tumor response to PD-1 antibody treatment." (PMID 37957902, 2024). "Radiation-induced cell damage leads to the accumulation of double-strand deoxyribonucleic acid (dsDNA) in the cytosol of tumor, stromal, endothelial, and immune cells, activating the cGAS-STING pathway." (PMID 39409947, 2024). "During tumor progression, the DNA of tumor cells is relatively fragile and prone to leakage, leading to activation of the cGAS-STING signaling pathway." (PMID 39170700, 2024). "This demonstrates the important role of tumor exosomal ENPP1 in inhibiting the cGAS‐STING signaling pathway." (PMID 38498770, 2024). "Inhibition of PP2A increases neoantigen expression on tumor cells, activates the cGAS/STING pathway, suppresses regulatory T cells, and increases cytotoxic T cell activation." (PMID 38932511, 2024). "Previous studies have demonstrated that blocking CD47 significantly enhances CD103+ dendritic cell absorption of tumor DNA, activating the cGAS-STING pathway." (PMID 39379603, 2024). "The frequencies of cGAShigh, STINGhigh, and cGAShigh/STINGhigh GCs were higher in dMMR GC compared to pMMR/EBV (−) GC, suggesting that the tumor cell-intrinsic expression of cGAS–STING is up-regulated in dMMR GC." (PMID 39242811, 2024). "The key player identified within these vesicles was plant-derived mitochondrial DNA (mtDNA), which, upon internalization by tumor-associated macrophages, activated the cGAS-STING pathway, shifting pro-tumor macrophages to an antitumor phenotype." (PMID 39450170, 2024). "Overall, our study reveals a mechanism by which tumor exosomal ENPP1 inhibits cGAS‐STING signaling through the hydrolysis of 2′3′‐cGAMP." (PMID 38498770, 2024). "cGAS-STING activity is vital for the anti-tumor effects of various chemotherapeutics including PARPi11,12,60." (PMID 38459088, 2024). "To summarize, LEV@DOX@REV facilitated systemic immune responses that prevented tumor recurrence and metastasis by activating the cGAS/STING pathway." (PMID 38868091, 2024). "The increased expression of STING cGAS pathway genes indicates that THT induces tumor cell death while triggering an innate immune response." (PMID 39872527, 2024). "One of the mechanisms by which cGAS/STING enhances anti-PD-1/PD-L1 efficacy is by increasing tumor infiltrating lymphocytes (TILs)." (PMID 39469633, 2024). "Cytoplasmic chromatin fragments comprise histone-bound DNA fragments and are associated with the activation of cGAS–STING-dependent innate immune signalling that promotes cellular senescence and tumour suppression." (PMID 38200309, 2024). "The cGAS–STING pathway has been described as one of the major innate immunity pathways that detects tumor-derived DNA and activates antitumoral immune responses." (PMID 38147007, 2024).
tumor (continued). "For example, during radiotherapy for cancer patients, a large amount of tumor‐derived DNAs are delivered from the extracellular space into DCs by direct endocytosis of exosomes, activating the cGAS–STING signaling pathway and increasing antitumor immunity." (PMID 38525112, 2024). "Cancer cell-derived DNA activates tumour-resident DCs, inducing the production of interferon type I through the cGAS/STING pathway." (PMID 38833685, 2024). "X-ray-induced DNA damage, coupled with the release of tumour cell nucleic acids following tumour cell death, efficiently activated cGAS/STING both in vitro and in vivo." (PMID 39403376, 2024). "Currently, several tumor treatment strategies based on the activation of the cGAS-STING pathway by Mn2+ have been developed." (PMID 38999073, 2024). "Studies have shown that cGAS plays a dual role, contributing to both anti-tumor response and tumor escape." (PMID 39050748, 2024). "To further define the relevance of the tumor‐derived exosomes and cGAS‐STING pathway, we investigated the effect of different concentrations of exosomes on the ISRE reporter activities." (PMID 38498770, 2024). "Collectively, these results strongly suggest that the activation of cGAS/STING signaling directly mediated the anti-tumor effects of PRMT3 KO or inhibition through activation of T cell-mediated anti-tumor immunity in HCC." (PMID 39256398, 2024). "The present study shows that TET2 upregulates tumor cGAS expression to produce cGAMP, which further activates STING pathway in endothelial cells, leading to tumor vascular normalization and enhanced intratumoral CD8+ T cell infiltration." (PMID 38177099, 2024). "The endogenous stimulation of the cGAS-STING pathway in cancer can occur through uptake of tumor cell derived DNA, which will be abundant in hypoxic and necrotic zones that promote DNA damage and nuclear leaks." (PMID 38389103, 2024). "Preclinical findings suggest that the use of suboptimal doses of DNA-damaging agents in combination with ICIs or other immunotherapeutics can effectively stimulate tumor-targeting immune responses by increasing the inflammatory response via cGAS activation." (PMID 38473997, 2024). "The main mechanisms by which mtDNA induces ICD in tumor immunotherapy involve the cGAS-STING signaling pathway, toll-like receptor 9, and NLRP3 inflammasome." (PMID 39916954, 2024). "It has been found that cell senescence is an important tumor inhibition mechanism, and cytosolic DNA activation of the intrinsic cGAS–STING signaling pathway is believed to play a role in cell senescence." (PMID 38525112, 2024). "Mechanistically, TET2 mediated IL-2/STAT5A signaling epigenetically upregulates tumor cGAS expression and produces cGAMP." (PMID 38177099, 2024). "CDDP induces DNA fragment release during tumor cell killing, which is recognized by cGAS in tumor-infiltrating immune cells to facilitate downstream STING activation, while MSA-2 can further enhance this signaling." (PMID 38332843, 2024). "Activation of the cGAS-STING pathway in non-tumor cells by NK cells triggers a potent NK cell response, culminating in tumor elimination—a phenomenon known as “bystander effect”." (PMID 39834588, 2024). "For example, the extracellular matrix has been shown to signal for an immunosuppressive phenotype in tumor cells via mechanotransduction from stress fibers leading to autophagic degradation of cGAS." (PMID 38659582, 2024). "Prolonged activation of the cGAS pathway has been shown to lead to immune dysfunction, as well as an immunosuppressive tumor microenvironment." (PMID 39050748, 2024). "Numerous studies have demonstrated that activating the cGAS-STING pathway can influence the efficacy of tumor immunotherapy." (PMID 39464890, 2024). "Here, we provide a comprehensive description of the two key signaling components, PRMT1 and cGAS, in the PRMT1-cGAS-STING signaling pathway for therapeutic intervention to augment anti-tumor immunity." (PMID 40018367, 2024).